CA2 (carbonic anhydrase 2)
Diseases named in the same sentence as CA2 in open-access papers (continued):
Sharing a sentence is not in itself a finding about the gene and the disease.
cancer (continued). "Meanwhile, we found that the expression of CA2 and TSPAN1 was significantly different between cancer tissues and normal tissues at protein level (all p < 0.05)." (PMID 34657172, 2022). "Several studies indicate that co-regulation of K+ (Kv, KCa2+) and Ca2+ channels (P2X7 receptor, CRAC, TRP, voltage-gated Ca2+ (Cav) channels) plays a significant role in cancer cell progression, growth, proliferation, and invasion/migration." (PMID 36612099, 2022). "H2O2 secreted by neutrophils relies on the Ca2+ channel to kill cancer cells, which regulates the expression of transient receptor potential cation channel subfamily M member 2 (TRPM2) to inhibit cancer-cell proliferation." (PMID 36230676, 2022). "MALAT1 has been found to promote cell proliferation and migration of cancer cells by regulating the expression of genes promoting metastases, e.g., RASSF6, HNF4G, CA2, ROBO1, MIA2." (PMID 35887000, 2022). "Cancer cells express Ca2+ channels that are not present in normal cells, and changes in their expression levels are frequently observed." (PMID 37573463, 2023). "However, in several cancer types, it remains unexplored how Ca2+ entry via the STIM1/Orai1 machinery affects the various cell cycle effectors, either directly via Ca2+-binding proteins or indirectly via transcription factors, Ras/ERK, or PI3K/Akt pathways." (PMID 36612099, 2022). "The possibility of targeting SOCE has already been reported in several reviews; but since Ca2+ channels are expressed in the majority of cancers, it is difficult to distinguish whether SOCE targeting would impact cancer cells or CSCs." (PMID 36142596, 2022). "However, many Ca2+-associated channels, proteins, and kinases have not been investigated, and for most of the signaling pathways that have been studied, the specific mechanisms in migration, invasion, and metastasis of different types of cancers are only just beginning to be understood." (PMID 36071984, 2022). "Ca2+-activated Cl− channels (TMEM16, also known as anoctamins) perform important functions in cell physiology, including modulation of cell proliferation and cancer growth." (PMID 35207044, 2022). "Moreover, in contrast with expressed potential drug targets, Ca2+ channels, such as those of the TRP family, have altered expression in cancer cells but highly restricted tissue distributions." (PMID 32807785, 2020). "Unlike CA1, detection of CA2 mRNA expression using RNA sequencing showed a more widespread upregulation in cancers." (PMID 29495652, 2018). "Additional candidates include GPRC6A, a Ca2+ activated G-protein coupled receptor proposed to be identical to mAR or the zinc transporter ZIP9 also proposed to fulfill the role of mAR in cancer cells." (PMID 27027435, 2016). "In the present review, we present an up-to-date and critical view on Ca2+ permeable ion channels, with a major focus on TRPs, SOCs and PIEZO channels, which are modulated by tumour hypoxia and acidosis, as well as the consequent role of the altered Ca2+ signals on cancer progression hallmarks." (PMID 35806388, 2022). "Further analysis of an external CRC dataset and various literature sources revealed that CA2, CA7, and ITM2C could act as gene signatures for the early detection of CRC and showed the potential to regulate cell growth and division in a manner that could prevent cancer progression." (PMID 37895185, 2023). "For cancer vs. non-cancer prediction, the top-performing model included the plasma concentrations of ARG1, CA2, F13A1, and S100A12, achieving an mAUROC of 85.3% (72.8–97.8% (95% CI))." (PMID 41155404, 2025). "As a Ca2+-permeable nonselective cation channel, TRPV3 can recognize thermal stimulation (31–39 °C), and it plays an important regulatory role in temperature perception, pain transduction, skin physiology, inflammation, cancer and other diseases." (PMID 36677834, 2023).
tumor (106 papers, 2009 to 2026). "Hypoxia and acidic pHe regulate the expression and/or activity of several Ca2+-permeable channels, which are linked to tumour aggressiveness." (PMID 35806388, 2022). "However, tumor cells often exhibit an intracellular alkaline pH, so that acidification as a result of CA2 inhibition causes a shift towards a physiological pH value." (PMID 31262047, 2019). "Immune infiltration analysis demonstrated that CA2 expression was significantly correlated with multiple immune cell subsets, suggesting its role in shaping the tumor immune microenvironment." (PMID 41993224, 2026). "According to the immunohistochemistry results, it was found that CA2 showed a low expression status in the tumor group, which was consistent with the results of the GEPIA database analysis." (PMID 40995432, 2025). "Cluster2 was enriched with cytoskeleton and metabolism-related factors, such as ARPC3 and CA2, where CA2 participates in regulating the cellular pH and ion balance, and its expression changes suggest significant alterations in the tumour microenvironment." (PMID 40539065, 2025). "Several studies have shown that CBD can lead to apoptosis through stress on the endoplasmic reticulum in tumor cells, through the CA2+-dependent pathway, leading to disruption of the integrity of the mitochondrial membrane." (PMID 39453093, 2024). "To provide further support for the proliferative effect of tumor organoid factors on SMCs, we also assessed the expression of S100A4, a Ca2+-binding protein associated with SMC proliferation." (PMID 38339292, 2024). "Specifically, carbonic anhydrase 9 (hCAIX) and carbonic anhydrase 2 (hCAXII) are crucial in acidifying the tumor environment and promoting tumor cell invasion and metastasis." (PMID 39104400, 2024). "In summary, the triterpene glycoside, CA2-2, isolated from the sea cucumber C. japonica, is a small bioactive molecule capable of inducing apoptosis in tumor cells via the caspase-dependent intrinsic pathway." (PMID 38248645, 2023). "The immunohistochemistry results in HCC revealed that CA2 expression levels were lower in tumor tissues than in adjacent tissues." (PMID 36631756, 2023). "We and others have previously shown that a major factor in TMZ resistance in GB stem cells and recurrent tumor tissue is carbonic anhydrase 2 (CA2)." (PMID 38139457, 2023). "We found that all patients showed a decreased proportion of CA2-positive (enterocyte marker) cells in tumor tissues, which was verified by immunohistochemical (IHC) staining." (PMID 35974387, 2022). "In a spatial context, we also observed high expression of PLVAP and CA2 within the tumor infiltrated region." (PMID 36180422, 2022). "In this regard, by analyzing GSCs resistant to TMZ treatment, we and others have shown previously that a major factor of TMZ resistance in GBM stem cells and recurrent tumor tissue is Carbonic Anhydrase 2 (CA2)." (PMID 35008590, 2021). "As a metabolic consequence, CA2 maintains glycolysis in tumor cells, thus supporting the “Warburg effect”, prioritizing glycolysis as a major source of energy." (PMID 35008590, 2021). "In six out of eight pairs an up-regulation of CA2 in the recurrent tumor was observed, whereas in the remaining two pairs a down-regulation was displayed." (PMID 31262047, 2019). "The importance of S100A4, a Ca2+-binding protein, in mediating tumour cell migration, both intracellularly and extracellularly, is well documented." (PMID 23469180, 2013). "Our findings revealed that carbonic anhydrase 2 (CA2) could bind stably to AFB1 (Vina score = -7.8 kcal/mol) and possessed diagnostic potential for distinguishing tumor samples from normal ones (AUC = 0.819)." (PMID 41993224, 2026). "CA2, identified as a biomarker in gastrointestinal tumors, plays a critical role in regulating intracellular pH homeostasis despite the acidic extracellular tumor environment." (PMID 41155404, 2025).
tumor (continued). "Moreover, the CytoTRACE2-Potency analysis characterized all tumor cell subpopulations, indicating that the majority of C1 CA2+ TCs and C3 ITLN1+ TCs were differentiated." (PMID 40842994, 2025). "C1 CA2+ TCs exhibited greater abundance in tumor stages 0, I, and III." (PMID 40842994, 2025). "We found that CA2-2 also effectively inhibits the formation and growth of tumor cell colonies." (PMID 38248645, 2023). "This supports the notion that CA2 could be involved in proton/lactate symport in GBM cells thereby supporting the so-called “Warburg effect” in tumor cells by maintaining glycolysis as a major source of metabolic energy." (PMID 35008590, 2021). "The upregulation of Ca2+/calmodulin-dependent protein kinase II and HIF1a in CC cells promoting tumor cell invasion and metastasis is related to aerobic glycolysis, and the activation of downstream factors MMPs and EMT also participates in tumor cell migration." (PMID 34127021, 2021). "However, tumor cells often exhibit an alkaline pH, so that acidification as a result of CA2 inhibition leads to a physiological pH, thereby enhancing the uptake of TMZ into tumor cells." (PMID 35008590, 2021). "We also showed that KCa and Ca2+ channels are differentially expressed according to tumor site." (PMID 31010205, 2019). "Thus, the diagnostic power of CA2 on NPC has comparable evidence from other solid tumor types, and it potentially reflects the inflaming tumor microenvironment." (PMID 28117408, 2017). "Yet, administration of dantrolene, an inhibitor of the Ca2+-dependent proteases, did not modify tumor-induced body weight loss and muscle wasting in the AH-130 hosts." (PMID 28469577, 2017). "When published data are taken into consideration, it is apparent that increased cytosolic calcium could inhibit mTOR to induce autophagy in human tumor cell lines and this pathway is mediated by Ca2+/calmodulin-dependent kinase kinase-β (CaMKK-β) and AMPK." (PMID 23847620, 2013). "Furthermore, scRNA-seq and pseudotime trajectory analyses revealed heterogeneous and dynamically downregulated CA2 expression across hepatocyte subpopulations, indicating a potential "gene-switch" pattern of this gene during the state transition of tumor cells." (PMID 41993224, 2026). "Altered expression and function of Ca2+ channels, pumps, exchangers, and binding proteins disrupt the finely tuned balance of Ca2+ influx, efflux, and intracellular storage, leading to aberrant signalling that promotes tumour proliferation, migration, survival, and metastasis." (PMID 41226294, 2025). "In addition, elevated CA2 suppressed tumor cell growth both in vitro and in vivo." (PMID 37466419, 2023). "VEGF-A induces carbonic anhydrase 2 (CAII), which reduces lactate acidosis in the tumor environment and enhances TEC survival." (PMID 35681715, 2022). "As expected, the tumor cells tended to show lower expression of differentiation genes such as enterocyte markers (CA1, CA2, and CLCA1) and endocrine cell markers (PYY and GCG)." (PMID 35974387, 2022). "The Ca2+-binding protein S100A4 and its interacting partner, Ca2+-dependent protein crosslinking enzyme tissue transglutaminase (TG2), promote tumor cell migration." (PMID 34282767, 2021). "However, aspirin did not affect the expression of the tumor-associated CA2, CA9 and CA12." (PMID 33917483, 2021). "Studies have shown that the anti-tumor effect of 5-FU has a certain correlation with PTGS2, NR3C2, CA2 and MMP1." (PMID 34125845, 2021).
tumor (continued). "In tumour cells chorein up-regulates ORAI1, a Ca2+-channel accomplishing store operated Ca2+-entry (SOCE) upon stimulation by STIM1." (PMID 28743945, 2017). "We then showed that the tested marine drugs (CA2, PMA, and ILQ) were able to induce the expression of autophagic proteins involved in autophagy signaling in human tumor cells (SCC-11, U87-MG, and RKO) in vitro." (PMID 27537898, 2016). "We also identified abundant expression of proteins involved in angiogenesis (ANXA2, CA2, ATP5B and HSPB1) in MDCKYBX1 tumours." (PMID 25980435, 2015). "Among the members of the CA isozyme family, CA2, CA9, and CA12 have been shown to be related to tumor genesis." (PMID 24959000, 2014). "We classified a total of 7,759 tumor cells into separate subpopulations based on their DEGs and designated each cluster according to its most prominently expressed marker gene: C0 NAP1L1+ TCs, C1 CA2+ TCs, C2 MKI67+ TCs, and C3 ITLN1+ TCs." (PMID 40842994, 2025). "Mapping tumor subpopulations onto this trajectory revealed that C0 NAP1L1+ TCs and C2 MKI67+ TCs generally occupied the early pseudotime segment, C3 ITLN1+ TCs were situated in the intermediate region, and C1 CA2+ TCs were primarily found in the late segment." (PMID 40842994, 2025). "CA2 and CA4 occur in healthy human kidneys, whereas CA9 is only present in tumor tissue." (PMID 33276608, 2020). "Interestingly, we observed the abundant expression in the tumours of several proteins known to be involved in angiogenesis, including ANXA2, CA2, ATP5B and HSPB1." (PMID 25980435, 2015). "In light of recent findings that SOCE promotes carcinogenesis and proposals to use inhibitors of SOCE for anticancer therapy, our findings demonstrate that drugs inhibiting the Ca2+ channels that mediate SOCE would compromise antitumour immunity and promote tumour growth." (PMID 23922331, 2013). "Collectively, our results suggest that AFB1 may contribute to the development of TACE nonresponse by downregulating CA2, which in turn mediates the regulation of tumor heterogeneity and immune remodeling." (PMID 41993224, 2026). "Furthermore, we observed that CA2 was increased in CA9-ko and NHE1/CA9-dko tumor extracts." (PMID 28055960, 2017). "Transcriptomic data from recurrent tumor tissues and TMZ-resistant GSCs previously revealed consistently enhanced levels of CA2, however, no functional data on CA2 in GBM cells and GSCs were available." (PMID 35008590, 2021). "Although TSCC tumor samples and TSCC15 cells also express CA2 and CA12, our in-house RNA-seq data showed that the expression levels of CA2 and CA12 were not altered when the expression of 887S or 887L was modulated." (PMID 34493285, 2021). "Meanwhile, CA2 was identified as the core molecule linking AFB1 exposure to TACE nonresponse, with its expression consistently downregulated in HCC tumor tissues, TACE nonresponders (log2FC = -1.063, P.adj = 0.0001), and AFB1-treated liver cells (log2FC = -0.978, P.adj = 0.005)." (PMID 41993224, 2026).
infection (14 papers, 2008 to 2023). The state of being infected such as from the introduction of a foreign agent such as serum, vaccine, antigenic substance or organism. "Therefore, we investigated if intracellular S. aureus interfered with host cell Ca2+ signaling and thus may activate signaling pathways and Ca2+-sensing proteins implicated in infection-induced host cell death." (PMID 33323513, 2020). "Ca2+-dependent protein kinases have been predicted to mediate signaling following Ca2+ influx after pathogen infection." (PMID 36212377, 2022). "Meanwhile, mid-intestinal activity of Ca2+, Mg2+-ATPase at 24 h, 48 h and 72 h post-infection (P < 0.05) was significantly reduced compared with the control group." (PMID 28484272, 2017). "Calprotectin consists of the Ca2+-binding proteins S100a8 and S100a9 that are induced in epithelial cells in response to tissue damage and infection." (PMID 23241281, 2012). "It is also worth highlighting the induction of genes CA2, CA and ANNAT4, and of kunitz protease inhibitors (KPIs)—which show endopeptidase inhibitor activity —because they are important elements of plant defenses against pathogen infection." (PMID 36555436, 2022).
neurodegenerative disease (7 papers, 2016 to 2025). A disorder of the central nervous system characterized by gradual and progressive loss of neural tissue and neurologic function.
cardiac diseases (4 papers, 2022 to 2024). "Currently, significant progress has been made in understanding the function of Ca2+ channels in a healthy heart, but there is still a limited amount of data on cytoarchitectonics and the physiology of Ca2+ channels in the cardiovascular cells associated with heart diseases." (PMID 37958665, 2023). "The purpose of this review is to highlight the little-studied aspects of the effect of Ca2+ channel dysfunction on the development of chronic and hereditary heart diseases." (PMID 37958665, 2023). "Cardiac ryanodine receptor (RyR2), the Ca2+ release channel of the sarcoplasmic reticulum, is believed to be a good therapeutic target in a group of certain heart diseases, collectively called cardiac ryanopathies." (PMID 35457253, 2022). "In addition, the contribution of posttranslational modifications of Ca2+ channels and the defects of Ca2+ handling proteins to the development of potentially lethal heart diseases are still poorly understood." (PMID 37958665, 2023). "K914R mutation of TRPM4 is a Ca2+-activated nonselective cation channel linked to human cardiac diseases." (PMID 35813831, 2022).
cardiovascular diseases (4 papers, 2018 to 2024). "Activation of Ca2+/calmodulin-dependent protein kinase (CaMKII) has been proved to play a vital role in cardiovascular diseases." (PMID 34194608, 2021). "Studies investigating activity and expression of carbonic anhydrases in cardiovascular disease have found elevated CA1 and CA2 expression in diabetic ischemic cardiomyopathy as well as elevated expression of CA2 and CA4 in patients with hypertrophic hearts." (PMID 38500750, 2024).
psychiatric disorder (4 papers, 2019 to 2022). A disorder characterized by behavioral and/or psychological abnormalities, often accompanied by physical symptoms. "In general, Ca2+ channels play central roles in neuronal functions, including neuronal excitability, neurotransmitter release, synaptic plasticity, and gene regulation, and genes that encode Ca2+ channels have been found to be associated with psychiatric disorders." (PMID 33644051, 2021). "Nevertheless, burgeoning research into this area has established the role of CA2 in social memory processes, with a particular focus on social recognition, and as such, dysfunction in this area has been implicated in the social impairments common to a number of psychiatric diseases." (PMID 31632251, 2019).
kidney diseases (2 papers, 2019 to 2022). "Calpains, a family of Ca2+-dependent cysteine proteases, play a pivotal role in the pathogenesis of renal diseases." (PMID 35155498, 2022). "The mTOR-independent autophagy-regulating pathways, including JNK-beclin-1-PI3KC3 pathways, as well as the p38, NFkB, Akt, Ca2+-calpain, and cAMP-Epac-PLC-ε-IP3 pathways, are relevant to kidney diseases." (PMID 31382550, 2019).